MET (MET proto-oncogene, receptor tyrosine kinase)
Diseases named in the same sentence as MET in open-access papers (continued):
Sharing a sentence is not in itself a finding about the gene and the disease.
tumor (continued). "HGF activates MET, expressed on tumor cells, and drives resistance to EGFR-targeted therapy by triggering ERK and PI3K/AKT pro-survival signaling and by promoting epithelial-mesenchymal transition." (PMID 28968967, 2017). "The tumor samples collected during the trial were examined for MET protein expression by IHC and MET gene copy number by FISH." (PMID 29246028, 2017). "It was demonstrated that VEGF suppresses HGF-dependent MET phosphorylation and tumor cell migration through the formation of a VEGFR2/MET heterocomplex." (PMID 29270405, 2017). "To further prove the identity of LcPDXs with primary tumours, we performed targeted mutation sequencing using a panel of 50 genes frequently mutated in human cancers and FISH analysis for MET gene amplification." (PMID 28751748, 2017). "Confirmation of MET amplification by fluorescence in situ hybridization (FISH) was performed only in samples with MET positivity on immunohistochemistry (2+ or 3+ staining intensity in >50.0% of the tumor cells according to the Metmab criteria)." (PMID 29163842, 2017). "FISH analysis also suggested that concurrent genetic alteration of EGFR and MET occurred in individual tumor cells." (PMID 28287179, 2017). "MET activation has been proven to play a critical role in the pathogenesis and progression of many tumor types." (PMID 29088883, 2017). "We assessed cell proliferation in vitro and tumor growth/stroma formation in derived xenograft models in response to a MET TKI (SGX523) and correlated with EGFR-MET dimerization assessed by Förster Resonance Energy Transfer (FRET)." (PMID 28141869, 2017). "More commonly, HGF is present in the tumor microenvironment and activates MET expressed on tumor cells in a paracrine fashion." (PMID 28420162, 2017). "IHC revealed similar levels of necrosis, as well as higher c-MET expression in HCC827ErlRes than HCC827 tumours, in accordance with the 89Zr-onartuzumab PET and biodistribution data." (PMID 28315949, 2017). "These include EGFR IHC/FISH, FGFR FISH, MET IHC and PD-L1 IHC for respective targeted therapy agents in a variety of tumor histologies." (PMID 29246028, 2017). "We demonstrated that SRI31215, an inhibitor of pro-HGF activation, blocked crosstalk between tumor cells and fibroblasts in MET-amplified NSCLC cells." (PMID 28420162, 2017). "Strikingly, even submillimeter SKOv3 tumor deposits were observed subcutaneously in real time, revealing the high sensitivity of the fluorescence imaging device in detecting c-MET expressing tumors." (PMID 28485003, 2017). "This correlated with downregulation of c-MET protein on ex vivo IHC, while tumour necrosis levels were similar in NVP-AUY-922-treated and vehicle-treated animals." (PMID 28315949, 2017). "In this study, as with others, c-MET shows relevant overexpression in normal pancreatic tissue, excluding it as target for tumor-specific molecular imaging applications." (PMID 28915633, 2017). "Quantitative subcellular resolution intravital imaging revealed very high levels of GFP-c-MET in tumor lesions and in single isolated cells surrounding them, relative to normal sebaceous glands." (PMID 28485003, 2017). "HCC827 tumours in the present study showed high contrast and c-MET-specific 89Zr-onartuzumab uptake at a tracer protein dose of 10 μg." (PMID 28315949, 2017). "When EGFR is inhibited in cancer therapy, tumor cells possibly evade death by increasing MET signaling." (PMID 28456787, 2017). "MET, the receptor for hepatocyte growth factor (HGF), has been implicated in driving tumor proliferation and metastasis." (PMID 28406969, 2017). "We found the MET mutation Y1248C in K562/IR cells, and METY1248C strongly activates MET and promotes tumor formation." (PMID 28418880, 2017). "In conclusion, c-MET and PDGFRα signalling are essential for the growth and/or survival of SS tumours." (PMID 28511645, 2017).
tumor (continued). "Our BsAb can inhibit HGF-induced growth and migration of c-MET-addicted tumor cells, promote the apoptosis of tumor cells, and rescue IL-2 secretion of Jurkat T cells." (PMID 28404966, 2017). "Given the critical roles of the MET/HGF pathway in tumor growth and development, various groups developed MET blocking antibodies." (PMID 28406969, 2017). "Significant difference in MET overexpression was found in tumor location, Lauren classification, clinical stages, pT status and pN status." (PMID 28052014, 2017). "In non-small cell lung cancer (NSCLC) a low frequency subclone with MET amplification was selected for during treatment with EGFR tyrosine kinase inhibitors (TKI), allowing for development of a resistant MET- amplified tumour." (PMID 28716075, 2017). "miR-199a-3p functions as a tumor suppressor and inhibits tumor metastasis by repressing various oncogenes, such as mTOR,aurora kinase A, and c-MET.Previous analysis have indicated that miR-199a-3p expression is inhibited in various cancer types." (PMID 28743276, 2017). "The receptor tyrosine kinase MET and its cognate ligand hepatocyte growth factor (HGF) have been implicated in diverse aspects of tumour pathobiology, including tumour growth, survival, neoangiogenesis, invasion, and dissemination." (PMID 28103611, 2017). "Estrogen receptor 1 (ESR1), which mediates ULM development and appears to be expressed in ULMS and c-MET cells, acts in tumor dissemination by activating mitogenic signaling pathways." (PMID 29295562, 2017). "Mutations in the MYD88, MET, and APC genes were found in tumor samples from 2 out of 11 patients who relapsed later, and none were found in patients without relapse (0/33) (p=0.054)." (PMID 28152507, 2017). "Both HGF inhibition and c-MET blockade (using the small molecule c-MET inhibitor Compound-A) alone resulted in tumor reduction to a similar extent as that observed with gemcitabine." (PMID 29100344, 2017). "A tumour can compensate for EGFR (HER1) blockade through the activation of alternative signaling pathways such as amplification of MET as well as through changes in tumour microenvironment." (PMID 28056859, 2017). "In summary, our data underscore a key role of the tumor microenvironment in acquired resistance to MET kinase inhibitors in MET-amplified NSCLC cells." (PMID 28968967, 2017). "Nuclear images of c-MET-overexpressing mice tumor models injected with 125I-MET4 were qualitatively and quantitatively comparable to the best images published previously." (PMID 28485003, 2017). "IHC showed a marked decrease in c-MET expression in the tumours, with similar levels of necrosis, in NVP-AUY-922-treated and in vehicle-treated animals." (PMID 28315949, 2017). "Examples include BRAF gene amplification in MEK inhibitor treated tumor, HER2 and MET amplification in anti-EGFRab treated tumor." (PMID 28915719, 2017). "Preclinical data indicate that a combination of VEGF pathway and MET inhibition can be effective in targeting tumour angiogenesis and suppressing tumour growth and metastasis." (PMID 28103611, 2017). "Previous studies have indicated MET overexpression activated MET signal pathway to promote tumor cell growth, survival, migration, and invasion as well as tumor angiogenesis." (PMID 28052014, 2017). "Our results demonstrate that elevated HGFR protein levels are associated with dedifferentiation and distant metastasis and MET copy number gains with dedifferentiation, tumor extent, lymph node, and distant metastasis." (PMID 27894094, 2017). "In mice bearing tumors derived from DA3 (murine mammary adenocarcinoma) cell line expressing high levels of c-MET, significantly higher signal intensity was detected, and in particular within the tumors when compared to the tumor periphery." (PMID 28485003, 2017).
tumor (continued). "What is important to note is that with sh-CBL, and MET small molecule inhibition, there is reduces the in vivo tumor growth beyond just sh-CBL." (PMID 28835699, 2017). "Another possible explanation is an artificial selection of cells with activated c-MET or PDGFRα from heterogeneous cell populations within a tumour during cell-line establishment." (PMID 28511645, 2017). "The antitumor activity of cabozantinib was also investigated in HCCs, which inhibits the migration and invasion of tumor cells by blocking the HGF- mediated MET signaling." (PMID 28903454, 2017). "SRI31215 or JNJ38877605 also overcame resistance mediated by HGF-producing fibroblasts, demonstrating that inhibition of HGF/MET signaling prevents tumor-microenvironment-mediated resistance to targeted therapy." (PMID 28420162, 2017). "The activation of these signaling molecules by MET plays a key role not only in the development of many cancers, but also in drug resistance mechanisms implemented by tumor cells." (PMID 28418880, 2017). "MiR-206 also promoted the myogenic differentiation and blocked the tumor growth in xenografted mice by the down-regulation of Met tyrosine-kinase receptor, the product of the MET proto-oncogene." (PMID 28615991, 2017). "c-MET is overexpressed in a broad spectrum of human solid tumors, and once activated, promotes tumor progression, invasion, metastasis, and angiogenesis." (PMID 28404966, 2017). "Given that the HGF/c-MET pathway is involved in multiple stages of HNSCC tumor progression, it is a highly promising therapeutic target for this disease." (PMID 28441771, 2017). "In vitro, our BsAb inhibited HGF-induced growth and migration of c-MET-addicted tumor cells, and promoted apoptosis in tumor cells, even more effectively than JNJ, a known c-MET inhibitor." (PMID 28404966, 2017). "Aberrant MET activation promotes tumor growth, anti-apoptosis, angiogenesis, invasion, and metastasis." (PMID 28247252, 2017). "It is well established that over-activated HGF/MET signaling increases invasive growth and metastasis by inducing motility of tumor cells and survival in remote tissue sites." (PMID 28456787, 2017). "For example, BsAb simultaneously targeting EGFRx c-MET produced synergies that inhibited tumor proliferation and metastasis more effectively." (PMID 28404966, 2017). "In this study, we demonstrated that downregulated miR-323a-3p due to IG-DMR methylation functioning as a tumor suppressor inhibited the epithelial–mesenchymal transition (EMT) progression by regulating MET/SMAD3/SNAIL circuit." (PMID 28837140, 2017). "We did not observe statistically significant correlation of rs11762213 with MET RNA expression in either tumor samples or normal controls (p > 0.1, two-sided rank-sum test)." (PMID 28358873, 2017). "To investigate if the activating Hh and MET signals are the consequence of gene amplification, as previously demonstrated, we performed FISH analysis on resistant tumor samples, by the use of specific probes for MET and SMO genes." (PMID 28416737, 2017). "Immunoblot analyses of resected tumours demonstrated that TAS-115 treatment inhibited the phosphorylation of c-MET, AKT and ERK 1/2." (PMID 28511645, 2017). "These single cells with higher GFP-c-MET levels were correlated to early tumor aggressiveness and preceded the formation of local and distal metastases." (PMID 28485003, 2017). "The reported biodistribution data for the resistant tumours, however, excluded cystic areas, which affected approximately half of the resistant c-MET-upregulated HCC827-GR6 tumours." (PMID 28315949, 2017). "c-MET signaling is transiently activated in physiological process, but often constitutively activated in tumor cells." (PMID 28817103, 2017). "Using an orthotopic model of PC we have shown that “triple therapy” (inhibition of both HGF and c-MET combined with gemcitabine) resulted in the greatest reduction in tumor volume compared to each of the treatments alone or in dual combinations." (PMID 29100344, 2017).
tumor (continued). "MET-IHC (SP44 Ventana Medical System, Roche) was used to detect MET overexpression, which was defined as a staining intensity of 2+ or 3+ (≥10% of tumor cells with membrane or cytoplasmic staining of moderate or strong intensity)." (PMID 27013592, 2016). "After confirmation of its purity and functionality, we showed that the inhibitory ability of the anti-MET BpAb was significantly higher than the parental mAbs as assessed in cell-based assays and more importantly in a tumor xenograft mouse model." (PMID 27546726, 2016). "FACS analysis was used to compare the binding of ABT-700 to human tumor cell lines that express c-Met or harbor MET amplification." (PMID 26879245, 2016). "The tyrosine kinase c-MET has been reported to promote tumor formation and resistance to DNA damage, and expand the GBM stem-like cell population." (PMID 26700818, 2016). "On the other hand, inhibition of MET and VEGFR2 activity in tumor associated endothelial cells resulted in sustained growth inhibition." (PMID 27105539, 2016). "Afatinib resistant tumor cell killing by [ERBB3 + c-KIT + c-MET] knock down was significantly, though only partially i.e. ∼70% reduction, reduced by knock down of eIF2α, CD95 or Beclin1 (p < 0.05)." (PMID 26934000, 2016). "Herein we identified that TAS-115 is a potent inhibitor of FMS kinase as well as of VEGFRs/MET kinases, and showed its potent anti-tumor efficacy in a tumor-induced bone disease model." (PMID 27736957, 2016). "This proportion was significantly higher compared to MET amplification seen in anti-EGFR naïve tumor tissue-based biopsies (p < 0.001)." (PMID 27421137, 2016). "c-MET, the HGF receptor, is normally involved in cell growth, differentiation and neo-vascularization, but its dysregulation has been implicated in tumor formation, invasion and angiogenesis." (PMID 27322553, 2016). "Tumor cells harboring MET amplification display exquisite sensitivity to Met inhibitors, providing a rationale for the use of targeted therapies in patients carrying this lesion." (PMID 26987019, 2016). "Using our tumor genotyping panel, MET gene copy number gain was observed in two of 27 (7 %) samples." (PMID 27821131, 2016). "There still remains a substantial amount of tumor cells that are intrinsically resistant to the MET tyrosine kinase inhibitor." (PMID 27223439, 2016). "Akt activity is downstream of HGF/MET and is involved in tumor angiogenesis through increased secretion of vascular endothelial growth factor and by mediating the expressions of nitric oxide and angiopoietins." (PMID 27338367, 2016). "Animal tumor models were developed using NSCLC H1975 cells bearing the T790M mutation and H1993 cells with MET amplification." (PMID 27726115, 2016). "Expression of c-MET in tumor cells from cHL patients strongly correlated with a favorable prognosis with a higher 5-year survival rate compared with c-MET-negative tumor patients." (PMID 27923392, 2016). "PF-2341066 treatment dramatically suppressed PEL tumor progression including reducing ascites formation and spleen enlargement over this time frame and reduced expression of phosphor-c-MET and phosphor-ERK within the spleen tissues." (PMID 27923392, 2016). "The genomic DNA of cancer cell lines or tumor models were tested and compared with the MET gene CN and MET/CEN-7 ratio determined by SNP 6.0 and FISH, respectively." (PMID 26765781, 2016). "In conclusion, our analysis suggests baseline circulating MET and HGF as prognostic factors in second-line HCC, and tumor MET as a prognostic and predictive biomarker of HCC and tivantinib activity." (PMID 27579536, 2016). "Here, the authors sequence circulating tumour DNA and show that resistance to the third-generation inhibitor rociletinib is heterogeneous and recurrently involves somatic alterations of MET, EGFR, PIK3CA, ERRB2, and KRAS." (PMID 27283993, 2016).
tumor (continued). "As a pivotal oncogene for tumor progression influencing the HGF/c-MET pathway, MACC1, has been shown to participate in many biological mechanisms that produce poor clinical outcomes." (PMID 27581375, 2016). "A limitation of the current study is the limited number of patient tumor samples available for assessment of MET expression and c-MET amplification, precluding any assessment of correlation between MET expression and antitumor activity of LY2875358." (PMID 27422720, 2016). "The ability of the BpAb to affect HGF-independent MET activity in tumor cells displaying constitutive MET activation was investigated." (PMID 27546726, 2016). "HGF together with its receptor MET, triggers oncogenic signaling events which result in the mesenchymal transformation of tumor cells, resulting in attributes which promote tumor spread, including cell-scattering and invasion." (PMID 27058427, 2016). "It was concluded from these studies that activation of the HGF/MET pathway in tumor tissue plays significant roles in tumor progression and prognosis of locally advanced GC." (PMID 26716644, 2016). "We identified eight tumor cell lines exhibiting MET gene amplification as determined by fluorescent in situ hybridization (FISH) with an average ratio of MET and CEP 7 (a centromere control) copy numbers of 2 or greater." (PMID 26879245, 2016). "Another pathway HGF/c-MET/ETS-1 also plays a central role in tumor proliferation, invasion and metastasis." (PMID 27824903, 2016). "MET amplification was seen in 10 (1.7%; 95% CI: 0.01–3.14%) of 590 tumor tissue biopsies tested by both FISH and sequencing." (PMID 27421137, 2016). "JNJ-38877605 is a highly selective c-MET ATP competitive kinase inhibitor, which induces cell death in tumor cells overexpressing c-MET protein or expressing constitutively activated c-MET protein." (PMID 27322553, 2016). "Cohort 1 (n = 103) and 2 (n = 208) included resected liver metastases and tumor biopsies, respectively, tested for MET amplification using fluorescence in-situ hybridization [amplification: MET/CEP7 ratio ≥ 2.0]." (PMID 27421137, 2016). "Collectively, these data indicate that radiosensitization of GBM by MET inhibitors not only impairs tumor growth, but also depletes the GSC subpopulation responsible for tumor generation and recurrence." (PMID 27138567, 2016). "CAPP-Seq profiling of rociletinib-resistant (RR) tumours identified MET amplification as the sole somatic aberration emergent in RR tumours when compared to vehicle treated tumours." (PMID 27283993, 2016). "The expression of p-c-MET protein in harvested tumor tissues was lower in the SU11274 treatment group compared with controls." (PMID 27917934, 2016). "These insights indicate that simultaneous inhibition of the VEGFR- and MET-axis is a reasonable therapeutic strategy for bone metastasis as targets for both tumor growth and abnormal bone metabolism." (PMID 27736957, 2016). "Unexpectedly, some NSCLCs with high MET expression (IHC 3+) and amplification exhibited tumor progression following treatment." (PMID 27013592, 2016). "miR-199a can downregulate mTOR (mechanistic Target of Rapamycin), c-MET (protein encoded by the MET gene), and its downstream effector ERK2, thus inhibiting cell proliferation, motility, and the invasive capabilities of tumor cells." (PMID 27775664, 2016). "SNP 6.0 and FISH are the methods that are conventionally used to evaluate MET copy number in cancer cell lines in vitro and tumor samples in vivo, respectively." (PMID 26765781, 2016). "In both CO7 and CO10, the normalized copy number of MET in ctDNA paralleled increasing tumour burden over the course of treatment, suggesting that MET copy-number gain is mediating resistance in these patients." (PMID 27283993, 2016). "In this study, we sought to employ ddPCR assays to absolutely quantify the MET copy number in cancer cell lines and tumor samples and compared our results with those obtained using SNP 6.0 and FISH for the same samples." (PMID 26765781, 2016).